RGS11 (regulator of G protein signaling 11)
Description:
Inhibits signal transduction by increasing the GTPase activity of G protein alpha subunits thereby driving them into their inactive GDP-bound form.
Synonyms: RS11
Tractability: Antibody: its Gene Ontology location is reachable by antibodies, with high confidence.
Gene: Protein-coding gene on chromosome 16 (268,301 to 275,980, reverse strand). Ensembl gene ENSG00000076344.
Pathways (Reactome):
Metabolism of proteins: Cooperation of PDCL (PhLP1) and TRiC/CCT in G-protein beta folding
Signal Transduction: G alpha (i) signalling events
Gene Ontology:
Molecular function: G-protein beta-subunit binding; GTPase activator activity; GTPase activity
Biological process: G protein-coupled receptor signaling pathway; regulation of G protein-coupled receptor signaling pathway; intracellular signal transduction
Cellular component: protein-containing complex; cytoplasm; neuron projection; plasma membrane
Genetic constraint (gnomAD): Loss-of-function variants: 83 observed, 65.41 expected, observed/expected ratio (o/e) 1.27, 90% interval 1.06 to 1.52. The synonymous counts are far from expectation, so gnomAD's model fits this gene poorly and the ratio says little. Missense variants: 692 observed, 576.61 expected, observed/expected ratio (o/e) 1.2, 90% interval 1.13 to 1.28. Synonymous variants: 280 observed, 228.71 expected, observed/expected ratio (o/e) 1.22, 90% interval 1.11 to 1.35.
Homologues: Orthologues: chimpanzee RGS11 (97% identical), macaque RGS11 (85% identical), guinea pig RGS11 (80% identical), mouse Rgs11 (78% identical), pig RGS11 (77% identical), dog RGS11 (75% identical), tropical clawed frog rgs9 (65% identical), rabbit RGS11 (62% identical), zebrafish rgs11 (60% identical). Paralogues in human: RGS9 (51% identical), RGS7 (37% identical), RGS6 (35% identical), RGS12 (21% identical), RGS3 (21% identical), RGS22 (18% identical), RGSL1 (17% identical), RGS14 (14% identical), AXIN1 (14% identical), RGS20 (14% identical), RGS19 (13% identical), RGS5 (13% identical), and 11 more.
Diseases named in the same sentence as RGS11 in open-access papers:
RGS11 is named in the same sentence as 14 diseases in open-access papers, as found by Europe PMC text mining. Sharing a sentence is not in itself a finding about the gene and the disease. The quoted sentences say what the papers report.
lung carcinoma (5 papers, 2011 to 2024). "RGS11 is associated with TMPRSS2-ERG fusion, and is a biomarker of lung cancer." (PMID 33498739, 2021). "Even though there are no available data linking RGS11 with CRC development, it is worth mentioning that RGS11 is already recognized as a lung cancer biomarker whose activity was correlated with the formation of metastases." (PMID 38203748, 2024).
lung adenocarcinoma (3 papers, 2016 to 2023). A carcinoma that arises from the lung and is characterized by the presence of malignant glandular epithelial cells. "Overexpression of RGS11 gene, encoding for a regulator of G protein signaling 11, promotes cell migration and is associated with advanced stages and aggressiveness of lung adenocarcinoma." (PMID 31447885, 2019). "The present study is the first to identify a role of RGS11 in the promotion of cell migration of cancer cells and show its overexpression highly associated with poorer prognosis of patients with lung adenocarcinoma." (PMID 27105500, 2016). "Taken together, data support the idea that RGS11 overexpression is strongly associated with the aggressiveness of lung adenocarcinoma." (PMID 27105500, 2016). "We found that RGS11 was highly expressed in LN- and bone-metastatic tumors as well as advanced primary tumors in patients with lung adenocarcinoma." (PMID 27105500, 2016). "Using subtractive hybridization analysis, we found that RGS11 was highly expressed in the lymph-node metastatic tissues and bone-metastatic tumors obtained from patients with lung adenocarcinoma." (PMID 27105500, 2016). "Collectively, overexpression of RGS11 promotes cell migration, participates in tumor metastasis, and correlates the clinicopathological conditions of patients with lung adenocarcinoma." (PMID 27105500, 2016). "However, overexpression of RGS11 was found in samples of lung adenocarcinoma." (PMID 27105500, 2016). "In addition, to determine whether the expression status of RGS11 correlates with disease progression, 91 lung adenocarcinoma samples were analyzed." (PMID 27105500, 2016).
ovarian carcinoma (3 papers, 2022 to 2024). A malignant neoplasm originating from the surface ovarian epithelium. "This five-gene signature (RGS11, RGS10, RGS13, RGS4, and RGS3) is overexpressed in ovarian cancer and involved in extracellular matrix–receptor interaction, the TGF-β signaling pathway, the Wnt signaling pathway, and the chemokine signaling pathway." (PMID 39145770, 2024).
colorectal cancer (2 papers, 2011 to 2016). A primary or metastatic malignant neoplasm that affects the colon or rectum. "Increased expression of RGS11 is shown to be associated with oxaliplatin resistance in colorectal cancer." (PMID 27105500, 2016). "Additionally, RGS11 has also been validated as one of the genes upregulated in colorectal cancer and implicated in the acquisition of oxaliplatin resistance." (PMID 27105500, 2016).
prostate carcinoma (2 papers, 2019 to 2022). A carcinoma that arises from epithelial cells of the prostate gland. "Furthermore, authors revealed such genes for the TMPRSS2-ERG prostate cancer molecular subtype (B4GALNT4, ASRGL1, MYBPC1, RGS11, SLC6A14, GALNT13 and ST6GALNAC1)." (PMID 36077746, 2022). "Additionally, we revealed such genes for the TMPRSS2-ERG prostate cancer molecular subtype (B4GALNT4, ASRGL1, MYBPC1, RGS11, SLC6A14, GALNT13, and ST6GALNAC1)." (PMID 31447885, 2019).
glioma (1 paper, 2016). A benign or malignant brain and spinal cord tumor that arises from glial cells (astrocytes, oligodendrocytes, ependymal cells). "RGS3 and RGS4, which share a similar function with RGS11 in modulating Gαi/o activity are overexpressed in faster migrating glioma cells, which results in greater cell adhesion and chemotaxis." (PMID 27105500, 2016).
metastatic tumors (1 paper, 2016). "After subtractive hybridization, the RGS11 gene was shown by RT-PCR analysis to be highly upregulated in the metastatic tumors as compared with the corresponding primary tumors." (PMID 27105500, 2016).
cancer (3 papers, 2011 to 2021). A tumor composed of atypical neoplastic, often pleomorphic cells that invade other tissues. "The other host genes of SNPs in chemotherapy group, RGS1, and RGS11, have also been associated with the etiology and prognosis of cancer." (PMID 21698121, 2011).
tumor (3 papers, 2016 to 2022). "Characterization of the clinicopathological features of 91 patients showed that around 57.1% of the tumor samples displayed RGS11 overexpression that was associated with primary tumor status, nodal metastasis and increased disease stages." (PMID 27105500, 2016). "While all of the tumor cells at both diagnosis and relapse shared the two SNVs in CREBBP and RGS11, five additional mutations in NRF1, MARCKS, USP11, ELK1, and MYC were detected at diagnosis." (PMID 26527318, 2016). "Because of the limited LN tumor samples available, 12 pairs of lung primary and bone metastatic samples were used in the comparison of RGS11 expression in these two types of tumors." (PMID 27105500, 2016). "Five variables (LINC01089, RGS11, MXD3, BIRC5, and RAB30) of Sig27var25 are risk factors of poor OS and three of them remain risk factors of fatality after adjusting for age at diagnosis and tumor stages." (PMID 35681785, 2022). "Characterization of the clinicopathological features of the patients indicated that RGS11 overexpression was significantly associated with increased primary tumor status, nodal metastasis, and disease stages, but not related to gender or age." (PMID 27105500, 2016). "Cotransfection of RGS11 with additional protease genes such as uPA in CL1-0 cells significantly elevated the capability of cell and tissue invasion, confirming its newly-identified role in cell migration and participation in tumor metastasis." (PMID 27105500, 2016). "Around 57.1% (52/91) of the samples displayed moderate or strong RGS11-positive immunoreactivity in no less than 50% of the tumor cells." (PMID 27105500, 2016).
RGS11 also shares sentences with these, for which no sentence is quoted: adenocarcinoma (1 paper); Alzheimer disease (1); amyotrophic lateral sclerosis (1); cervical cancer (1); Obesity (1).